RPL13P12 (ribosomal protein L13 pseudogene 12)
Synonyms: RPL13_4_1521
Gene: Processed pseudogene on chromosome 17 (17,383,377 to 17,384,012, reverse strand). Ensembl gene ENSG00000215030.
Diseases named in the same sentence as RPL13P12 in open-access papers:
RPL13P12 is named in the same sentence as 3 diseases in open-access papers, as found by Europe PMC text mining. Sharing a sentence is not in itself a finding about the gene and the disease. The quoted sentences say what the papers report.
Atopic Dermatitis (1 paper, 2025). "Nousbeck showed that RPL13P12 is upregulated in infants (7–12 month old) with Atopic Dermatitis." (PMID 41010012, 2025).
RPL13P12 also shares sentences with these, for which no sentence is quoted: glioblastoma (1 paper); metastatic colorectal cancer (1).